MIR520B (microRNA 520b)
Synonyms: hsa-mir-520b; MIRN520B
Gene: MicroRNA gene on chromosome 19 (53,701,227 to 53,701,287, forward strand). Ensembl gene ENSG00000207722.
Gene Ontology:
Biological process: miRNA-mediated post-transcriptional gene silencing
Homologues: Orthologues: chimpanzee ptr-mir-520b (100% identical), macaque mml-mir-519a (97% identical). Paralogues in human: MIR519A2 (95% identical), MIR519B (95% identical), MIR520C (95% identical), MIR519C (93% identical), MIR520F (93% identical), MIR516A1 (92% identical), MIR516A2 (92% identical), MIR522 (92% identical), MIR523 (92% identical), MIR516B1 (89% identical), MIR518B (89% identical), MIR518E (89% identical), and 12 more.